CD34 (CD34 molecule)
Diseases named in the same sentence as CD34 in open-access papers (continued):
Sharing a sentence is not in itself a finding about the gene and the disease.
tumor (continued). "In this report, we describe six cases of CD34+ fibroblastic tumours found in the orbit and conduct a review of the literature discussing the clinical, histopathological and immunohistochemical features of the tumours found to date." (PMID 28449640, 2017). "Upon the simultaneous transplantation of human CD34+ hematopoietic stem cells (HSC) and human BC cell lines (BT474 and SK-BR-3), the NSG mice developed liver-associated tumor growth (BT474) or tumor cell effusion in the peritoneal cavity (SK-BR-3)." (PMID 27835865, 2017). "Moreover, to assess its potential role in tumor growth and angiogenesis, the expression of Ki67, CD34 and vascular endothelial growth factor receptor-2 (VEGFR2) were detected by immunohistochemistry in CRC cells tumors." (PMID 28420432, 2017). "Furthermore, Tgfbr2 cKO lung metastases expressed YFP and contained populations of CD34+ cells, recapitulating the hierarchy of the primary tumor of origin." (PMID 28219480, 2017). "Primary tumor and CD34+ BMC from the fibula bone were initially engrafted into NOG-A2 separately." (PMID 28008146, 2017). "Immunohistochemical staining with CD34 antibody was conducted to analyse the microvessel density in tumour nodules of miR‐384, PTN and control groups, and these microvessels (at 20×) were counted in five random microscopic fields to assess the tumour nodules in every group." (PMID 28557334, 2017). "The frequency of epithelial CD34+ cells within the tumor varied between mice, from 7% to 34%." (PMID 28219480, 2017). "We have found that BA could achieve a selective cytotoxic effect on AML tumor cells, instead of primary CD34+ cells, which shows potential application for anti-tumor drug development." (PMID 29212263, 2017). "To determine the effect of H2S on angiogenesis, we observed the MVD in dissected tumor tissues by anti-CD34 immunostaining and found that it was significantly increased with 25–100 μM NaHS treatment, suggesting that H2S had a pro-angiogenic effect in agreement with previous findings." (PMID 28698660, 2017). "Tumor cells showed strong positivity for CD34, vimentin and Bcl-2." (PMID 29075420, 2017). "Finally, in the experimental mouse model, we showed that curcumin inhibited HGF-stimulated tumor growth and induced an increase in E-cadherin expression and a decrease in vimentin, CD34, and vascular endothelial growth factor (VEGF) expression." (PMID 27525306, 2016). "We observed a reduced intra-tumor vessel density assessed by CD34 staining." (PMID 27788481, 2016). "However, PD98095 had no obvious effect on the growth of the SCLC tumor xenografts, and HIF-1a and CD34 expression in this tumor tissue showed only marginal changes." (PMID 27456341, 2016). "Interestingly CD7+/CD34+ cells of the slow developing T-ALL4 contained a genetic subclone recurrently selected in xenografts that harbours a deletion of the tumour suppressor IKAROS." (PMID 27191650, 2016). "Additionally, our findings of CD34+/CD45+ IFDUC1 MEC further support more undifferentiated tumor cells." (PMID 26968831, 2016). "Moreover, in vivo tumor formation was performed on nude mice model, and the tumor microvessel density (MVD) was determined by anti-CD34 staining in different groups." (PMID 27729020, 2016). "(Pro)renin receptor (red) was expressed by the EMA+ (green) cells within the tumor nests, as well as the CD34+ endothelium (green, arrows) and the outer pericyte layer (red, arrowheads) of the microvessels and OCT4+ (green) cells within the peri-tumoral stroma." (PMID 27730124, 2016). "In this present study we support the idea that the significant higher expression of known endothelial markers CD34 and PDGFRB noted on both normal and tumor ADSC could be linked with the potential of ADSC to differentiate into an endothelial-like lineage." (PMID 26968831, 2016). "Similarly, CD34 expression was reduced by 16-fold in tumor xenografts derived from Oct4A KD1 cells compared to only 2.5-fold decrease in Oct4A KD2 cells derived xenografts." (PMID 27390927, 2016).
tumor (continued). "The tumor cell proliferation and vascularity, which were evaluated by KI-67 and CD34, respectively, were markedly decreased in BCAT1 sh#1 rats than IDH1 WT rats (5.48% [IQR,–0.04–11.00] vs 33.86% [23.56–44.18]; p = 0.0001, and 1.22% [IQR, 0.71–1.72] vs 5.20% [2.44–7.95]; p = 0.0044, respectively)." (PMID 27626306, 2016). "Hence, the CD34+ bulge cells appear to be targeted in two-stage chemocarcinogenesis to become tumor-initiating cells." (PMID 27409834, 2016). "Tiny tumor blood vessels can be identified by CD34 staining." (PMID 27069921, 2016). "Differential diagnosis should include giant cell angiofibroma which is a highly vascular tumor comprising a spindle-cell proliferation with numerous multinucleated giant cells and pseudovascular spaces, and immunohistochemically positive for CD34, CD99, and vimentin." (PMID 26754205, 2016). "Immunohistochemically, the tumor showed strong and diffuse staining for CD34, bcl-2, and vimentin; other markers, such as pan-cytokeratins, EMA, desmin, alpha-smooth muscle actin, and S-100 protein, were negative and had a high mitotic index (seven mitoses per 10 high-power fields (HPF))." (PMID 25649645, 2015). "The tumor cells were positive for vimentin, alpha 1-antitrypsin, alpha 1-antichymotrypsin, and desmin, and partially positive for CD34 and alpha-SMA." (PMID 26366352, 2015). "PNS treatment could decrease the expression of miR-18a in tumor and further down-regulate CD34 and vWF that led to angiogenesis inhibition in tumors, while an opposite activity by PNS on angiogenesis was observed in heart." (PMID 26305257, 2015). "CD34 highlights the capillarized endothelial cells of the tumor’s microvascular bed." (PMID 26404250, 2015). "The immunohistochemistry test revealed 40% membranous staining with CD34 in the tumor cells." (PMID 26064131, 2015). "CD34 is closely related to tumor occurrence, development, and prognosis." (PMID 26788112, 2015). "CD34 expresses in vascular endothelial cells, tumor cytoplasm or membrane." (PMID 26136642, 2015). "As is known, CD34 is a good marker to reflect the density of blood vessels in the tumor." (PMID 26788112, 2015). "Instead, a concordant relation of CD68+ infiltrating cells with the CD34+ vessel number by IHC staining (rs = 0.277, p = 0.014) supported a positive role of infiltrated macrophages in tumor angiogenesis required for tumor growth and metastasis." (PMID 26315114, 2015). "On immunohistochemistry, the tumour was positive with CD34 and CD31." (PMID 26435872, 2015). "However, genistein did significantly reduce microvessel density, as reflected by decreased CD34 staining in tumor tissues, and it did so in a dose-dependent manner, with the strongest reduction observed in the 75 mg/kg/d group (p=<0.000)." (PMID 25605009, 2015). "All these described tumours share similar morphologic features and are characterized by bland ovoid to spindle-shaped cells with wispy collagen, variably sized thick-walled blood vessels and immunoreactivity to CD34." (PMID 26187500, 2015). "As known, CD34 is a good marker to reflect the density of blood vessels in the tumor." (PMID 26788112, 2015). "Comparison of the cellular co-localization of TLR7 or TLR8 with CD34 analyzed by immunofluorescence double staining revealed increased coexpression of TLR7 or TLR8 with CD34 in tumor cells, indicating that those cells were indeed cancer cells expressing the angiogenic surface molecule." (PMID 26134824, 2015). "The tumour cells consistently exhibit coexpression of desmin and CD34." (PMID 26187500, 2015). "Since endothelial cells seem to proliferate at periphery but not in the interior of the tumor, we quantified the CD34 staining associated with the tumor peripheral zone and with the normally-appearing breast tissue located at 1 cm from the tumor edge." (PMID 25652007, 2015). "In addition, in 1 case of a GBM in our study, CD34 highlighted not only endothelial cells, but also tumor cells." (PMID 25881913, 2015).
tumor (continued). "IHC revealed that the tumor diffusely expressed CD34, CD99, Bcl2, PAX8, NAB2, STAT6, and GRIA2." (PMID 26337721, 2015). "In addition, in 1 GBM where ERG only stained endothelial cells, CD34 stained both endothelial and tumor cells." (PMID 25881913, 2015). "Immunohistochemically, tumor cells were positive for vimentin, CD34, and AE1/AE3." (PMID 26090253, 2015). "Therefore, both the CD34-staining and the Map2-staining demonstrated histopathological differences between the three tumor zones." (PMID 25609379, 2015). "Finally, we sought to determine if CSF-1R was co-expressed with the stem and progenitor cell markers CD34, CD117, and CD133, since these markers have been associated with tumor initiating cells and as well as drug resistance." (PMID 25295160, 2014). "However, in the pyogenic granuloma portion, CD34 was almost negatively detected, whereas vimentin and Ki-67 were highly detected in the fibroblast-like tumor cells." (PMID 24934284, 2014). "Therefore the expression of CD34 and vWF, molecular markers of vascular endothelial cell, in tumor and heart tissue sections was further evaluated by IHC." (PMID 24903055, 2014). "After determining the number of blood vessels in tumor samples from 29 patients by immunohistochemistry, using an antibody against CD34+, which is a marker of the blood vessel endothelium, we classified the tumor samples in two groups: high or low levels of miR-141." (PMID 25003366, 2014). "Immunohistochemical staining of CD34 showed that silencing endogenous EIF5A2 could reduce tumor MVD, a marker for angiogenesis." (PMID 25071013, 2014). "In addition, qPCR confirmed that the CD34− tumor cells express negligible levels of CD115 compared to the TAMs, and CD115 immunolabeling within tumor sections was accordingly restricted to immune cells." (PMID 25294815, 2014). "The increase in CD34 expression after concurrent chemoradiotherapy might represent a response of the tumor to treatment." (PMID 25373828, 2014). "On closer inspection, the poor performance of these algorithms was discovered to be a result of the immense diversity in both CD34 biomarker staining patterns as well as features of the cells in the large image set, all part of the inescapable heterogeneity of patient tumor samples." (PMID 24603893, 2014). "To determine whether the CD34− and CD34+ sphere-forming cells could initiate tumors in vivo, we inoculated Rag1 mice with 100 spheres from either CD34− or CD34+ tumor cells via the retro-orbital sinus, delivering them directly to the lungs." (PMID 25294815, 2014). "Some researchers believe that CD34 cannot make a distinction between the host’s primary blood vessels and the neo-angiogenesis; nonetheless, this marker is widely employed in appraising the vascular density in tumoral lesions." (PMID 25469359, 2014). "Proteins of CD34 were focally expressed in minor fractions of the tumor vessels (13.8%)." (PMID 24688535, 2014). "However, in PG, CD31 was highly detected in the small blood vessels of the tumor, whereas CD34 was rarely expressed." (PMID 24934284, 2014). "The tumor microvessel density was measured following staining with an anti-CD34 antibody." (PMID 24297248, 2014). "In our case, the tumor cells reacted with the endothelial cell marker CD34." (PMID 25184066, 2014). "In addition, immunohistochemical analysis revealed that tumor was positive for endothelial cell marker CD34 and occasionally positive for cell proliferative marker Ki-67." (PMID 25184066, 2014). "HNSCC patients are characterized by systemic immunosuppression, exhibiting increased populations of regulatory T cells and CD34+ progenitor cells, which suppress CD8+ T cell- and CD4+ helper T cell-mediated immunity at the primary tumor site and are associated with a poorer prognosis." (PMID 24698959, 2014).
tumor (continued). "CD34, a transmembrane glycoprotein expressed on hematopoietic stem and progenitor cells, endothelial cells, bone marrow progenitor cells, and many mesenchymal tumor cells, was detected in 52.9% of the malignant PT specimens." (PMID 24670249, 2014). "Tumor perfusion correlated with vessel size and vessel area ratio measured from CD34 staining." (PMID 24403176, 2014). "After the MRI, tumor vasculature was assessed by CD34 staining." (PMID 24403176, 2014). "Endothelial cells in tumor vessels stained positively for CD34." (PMID 24959254, 2014). "The tumor cells exhibited positive expression for CD34 and smooth muscle actin." (PMID 24137457, 2013). "When investigating CD34 expression on CML patient MDSCs we found that a median of 35% of MDSCs expressed CD34 demonstrating that some tumor cells may be accounted for as MDSCs." (PMID 23383287, 2013). "The microvessel density (MVD) can be assessed by CD31 and CD34 staining and gives important information on tumor vascularization which might be important for a response to TKI treatment." (PMID 24086736, 2013). "The expressions of both CD34 and MR were associated (directly with p<0.001, and inversely with p<0.001, respectively) with tumor stage categorised into stage I and II as opposed to stage III and IV." (PMID 23555666, 2013). "However, since we show that 95% of CD34 positive cells in peripheral blood were Ph positive CD34 was used as a marker for CML tumor cells." (PMID 23383287, 2013). "Tumor vessels were positive for both CD34 and PAS (red arrows)." (PMID 23536763, 2013). "Moreover, when cultured under conditions that facilitate myeloid-cell development, CD34+ cells are instead redirected by the tumor to differentiate into endothelial cells." (PMID 24341512, 2013). "Moreover, we observed its moderate inhibitory effects on cell proliferation and tumor angiogenesis by CD34 staining, enhancing levels of caspase-3 protein and placing strong enhancing effect on apoptosis by TUNEL staining." (PMID 23325045, 2013). "These increases in levels of CD34+ immune inhibitory cells could be due to increased mobilization from the bone marrow due to tumor production of GM-CSF." (PMID 24202334, 2013). "The same research group identified bipotent CD44+ CD34− cells in ovarian cancer and demonstrated that, in addition to being capable of tumor regeneration, these cells also contribute to tumor vascularization by a mechanism that involves inhibitor of kappa-kinase beta (IκK-β)." (PMID 23782518, 2013). "The immunohistochemistry for CD34 was examined on the primary tumor tissue sections to determine whether the suppression of primary tumor growth was a result of an antiangiogenic effect (i.e., the inhibition of microvessel formation) of the CXCR4 antagonist." (PMID 24137439, 2013). "Similarly, the representative tumor sections of human NBs also showed CD34-positive endothelial cells covered by abundant α-SMA-positive cells." (PMID 23930205, 2013). "The strongly positive staining of the tumor cells for CD34 and CD117 also suggested that it may be classified as an EGIST." (PMID 24137442, 2013). "The stromal loss of CD34 expression and acquisition of SMA myofibroblastic features may constitute a prerequisite for tumor invasiveness." (PMID 23469238, 2013). "Immunochemically, the tumor cells were positive for CD34 and alpha smooth muscle actin." (PMID 23714181, 2013). "The various factors secreted during necrosis could decrease the expression of CD34 stroma, facilitating tumor invasion." (PMID 23469238, 2013). "Furthermore, we show that most patients had CD34 cells (mostly tumor cells) expressing MDSC markers." (PMID 23383287, 2013). "Notably, DNA hypermethylation plays a central role in HSC protection from the activation of differentiation programs and is an epigenetic trait of a greater number of tumor suppressor genes in BCR-ABL1+/CD34+ compared with more differentiated progenitors." (PMID 24339928, 2013).
tumor (continued). "Furthermore, the angiogenic phenotype of ccRCC is also reflected by endothelial markers (CD31, CD34) or other tumor-promoting factors like Ki67 or survivin." (PMID 24086736, 2013). "We believe that several mechanisms may explain the promotion of tumor invasion that induces the transformation of CD34 fibrocytes to SMA myofibroblasts." (PMID 23469238, 2013). "CD34 marked both endothelium and spindle-shaped tumor cells." (PMID 23936513, 2013). "Also, immunohistochemistry for tumor sections revealed significant decreased expression of Ki-67 for proliferation, CD34 for microvessel density in the vascularized area of each tumor, and VEGF for angiogenesis." (PMID 23243443, 2012). "Finally, the effect of Drs B2 on tumor vascularization was investigated using CD34 labeling on tumor sections to quantify tumor blood vessels." (PMID 23028527, 2012). "Moreover, EP significantly suppressed the growth of U266 cells inoculated in female BALB/c athymic nude mice and immunohistochemistry revealed that EP effectively reduced the expression of STAT3 and CD34 in tumor sections compared to untreated control." (PMID 22260501, 2012). "Immunohistochemical detection of blood vessels in the tumor sections by anti-mouse CD34 antibody revealed that presented a mass of blood vessels in PBS or CIK group, whereas only few blood vessels which detected in AdCN205-GFP, AdCN205-IL12, CIK plus AdCN205-GFP or AdCN205-IL12 group." (PMID 23028626, 2012). "Moreover, we demonstrated that when phloroglucinol is orally administered, it significantly inhibits tumor growth and angiogenesis as well as CD45−/CD34+ progenitor mobilization into peripheral blood in vivo in the LLC-tumor-bearing mouse model." (PMID 22496756, 2012). "Quantification of CD34-marked microvessel density (MVD) in tumor xenograft samples indicated that samples derived from the group of HepG2 k tumor with control IgG revealed a 59.4±40.0% higher angiogenesis in comparison to the group of parental HepG2 tumor with control IgG (P<0.05)." (PMID 22615958, 2012). "Staining and quantification of CD34 positive staining vessels demonstrate significantly stronger staining and greater density in the central regions of tumor (P<0.001)." (PMID 23153292, 2012). "However, despite enhanced initial colonization in the lung, the later requirement for CD34 to maintain vascular integrity and promote tumor growth is dominant and CD34 ablation results in fewer detectable metastases at the day 12 time-point." (PMID 21494591, 2011). "Since the observed difference in s.c. tumor growth results from loss of CD34 in non-hematopoietic cells and we have previously shown increased vascular leakage in an inflammatory model, we focused our studies on quantifying vascular integrity in tumors." (PMID 21494591, 2011). "Immunohistochemically, tumor cells exhibit a positive reactivity for renin, vimentin and CD34." (PMID 21871063, 2011). "Immunohistochemistry showed the tumor cells to be CD34-positive and S-100-, ER- and PR-negative." (PMID 21714873, 2011). "In support of the second hypothesis, we found increased tissue carbocyanine leakage, altered vessel morphology and increased tumor cell extravasation in the lungs of Cd34−/− mice, compared to wildtype animals." (PMID 21494591, 2011). "Again, Cd34−/− animals reconstituted with wildtype bone marrow exhibited reduced tumor size 14 days post-s.c. injection, compared to Cd34+/+ animals reconstituted with wildtype bone marrow, as assessed by tumor volume measurements." (PMID 21494591, 2011). "These nonvascular BM-derived immune cells arise from the Sca1−Gr1+ mouse BM or CD34− human progenitor cell subpopulations, while Sca1+Gr1+ mouse BM or CD34+ human progenitor cells contribute to the endothelial cell and pericyte/vSMC populations within the tumor." (PMID 21785569, 2011). "Interestingly, carbocyanine fluorescence was more intense in Cd34−/− tumor tissues, as quantified and discussed in depth below." (PMID 21494591, 2011).